HOXC8 (homeobox C8)
Diseases named in the same sentence as HOXC8 in open-access papers (continued):
Sharing a sentence is not in itself a finding about the gene and the disease.
breast cancer (continued). "More importantly, depletion of HOXC8 leads to significant reduction of proliferation, colony formation and migration of breast cancer cells, which can be largely recovered by embigin knockdown, suggesting the functional linking between HOXC8 and embigin in breast cancer cells." (PMID 26090721, 2015). "Reciprocal Co-IP experiments and immunofluorescence staining confirmed the interaction between HOXC8 and ILF3, and the interaction mainly localized to the nuclei of breast cancer cells." (PMID 29296180, 2017). "In this study, we demonstrated that CDH11 transcription required the formation of a protein complex containing the HOXC8, NF90 and NF110 proteins in breast cancer cells." (PMID 29296180, 2017). "Subsequently, we performed survival analysis (Kaplan-Meier method, log-rank test) to assess the potential correlation between HOXC8/CDH11 expression and recurrence-free survival of breast cancer patients." (PMID 24810778, 2014). "Kaplan-Meier analysis further shows that both high HOXC8 and CDH11 expression correlate with poor recurrence-free survival of breast cancer patients." (PMID 24810778, 2014). "We demonstrated that the expression of adipogenesis-related genes HOXC8, HOXC9, FABP4 and HSL in adipose tissue adjacent to malignant breast tumors was down-regulated and the level of inflammatory cytokines, like TNFα and MCP-1, was up-regulated." (PMID 25291184, 2014). "In silico analysis of breast cancer patient datasets confirmed HOXC8’s significant repression in primary breast cancer tumors when compared to non-cancerous tissue." (PMID 39858044, 2025). "Analysis of the TCGA and METABRIC breast cancer datasets showed HOXC8 is rarely deleted in breast cancer and its expression does not correlate with copy number in breast cancer patients." (PMID 28202042, 2017). "Moreover, immunohistochemical staining of breast cancer specimens and normal breast samples showed that the expression of CDH11, ILF3 or HOXC8 was upregulated in breast cancer specimens." (PMID 29296180, 2017). "Online analyses using cBioPortal showed that expression of CDH11, ILF3 or HOXC8 was elevated in the advanced stages of breast cancer, where high mRNA expression levels of CDH11 or HOXC8 were detected in cancer stage IV, and high mRNA expression levels of ILF3 were detected in cancer stage IIIC." (PMID 29296180, 2017). "For example, miR-196a has been studied for its oncogenic roles in glioblastoma, pancreatic adenocarcinoma, breast cancer, oesophageal adenocarcinoma, and colorectal cancer, and shown to target HOX family genes (HOXA7, HoxB7, HOXC8, HOXB8, HOXD8), ERG, HMGA2, ANXA1, S100A9, SPRR2C, KRTS." (PMID 24621885, 2014). "CDH11 level was apparently correlated with HOXC8 expression because breast cancer cell lines with CDH11 expression all displayed relatively higher HOXC8 level compared with those with little or no detectable CDH11." (PMID 24810778, 2014). "Depletion of HOXC8 leads to the decrease in anchorage-independent cell growth, cell migration/invasion and spontaneous metastasis of breast cancer cells; however, suppressed tumorigenic events were fully rescued by ectopic CDH11 expression in HOXC8-knockdown cells." (PMID 24810778, 2014). "In breast cancer specimens, more than half of the cases exhibited strong and moderate positivity for CDH11, ILF3 or HOXC8, and only a few cases were negative for CDH11, ILF3 or HOXC8 (7.9% for CDH11, 13.2% for ILF3, and 13.2% for HOXC8)." (PMID 29296180, 2017).
prostate carcinoma (9 papers, 2011 to 2025). A carcinoma that arises from epithelial cells of the prostate gland. "In human prostate cancer, HOXC8 is both down-regulated as well as up-regulated in association with loss of tumour differentiation." (PMID 21712827, 2011). "For example, in prostate cancer, HOXC8 acts as an oncogene, while HOXB13 acts as a tumor suppressor gene." (PMID 36192513, 2022). "A dual role of HOXC8 has been described in prostate carcinoma, with a repressive function on gene induction at androgen response element-regulated genes as well as a function promoting invasiveness of this tumour." (PMID 21712827, 2011). "Although the underlying mechanisms were not clearly demonstrated, HOXC8 has also been reported to be associated with glioma, pancreatic duct carcinoma, and prostate cancer." (PMID 40701951, 2025). "HOXC8 has also been found to regulate proliferation, migration, and epithelial mesenchymal transition in triple negative breast cancer and invasion in prostate cancer." (PMID 32366326, 2020). "In several cancer types, HOXC8 is down-regulated, such as in oesophageal and prostate cancers." (PMID 21712827, 2011). "This suggests that HOXC8 may have a role in both the acquisition of the invasive and metastatic phenotype of this malignancy as well as in inhibiting androgen responsive prostate cancer cells." (PMID 21712827, 2011). "On the other hand, expression of HOXC8 is inversely correlated with the progression and metastasis of pancreatic ductal adenocarcinoma; HOXC8 inhibited androgen receptor signaling in human prostate cancer cells by inhibiting SRC-3 recruitment to direct androgen target genes." (PMID 35111675, 2021). "By contrast, GO analysis of the genes upregulated in the BPH-PCa group while downregulated in men with symptomatic BPH were several transcription factors related to prostate cancer, such as NKX3-1 and members of the HOX family like HOXB13, HOXB7, HOXD4, HOXC10 and HOXC8." (PMID 38201640, 2024).
non-small cell lung carcinoma (8 papers, 2014 to 2025). A group of at least three distinct histological types of lung cancer, including non-small cell squamous cell carcinoma, adenocarcinoma, and large cell carcinoma. "In non-small cell lung cancer, HOXC8 acted as the transcriptional activator to strengthen TGFβ1 expression, promoting cell growth and metastasis." (PMID 33758619, 2021). "In another study, HOXC8 levels were increased in non-small cell lung cancer and was correlated with lymph node metastasis, differences that were thought to be mediated by TGFβ1." (PMID 32366326, 2020). "HOXC8, as a transcriptional activator, induces the expression of transforming growth factor-β-1, which leads to the increase in the proliferation, anchorage-independent growth and migration of non-small cell lung cancer." (PMID 34732138, 2021). "In the present study, we investigated the roles of HOXC8 in non-small cell lung cancer (NSCLC)." (PMID 29367650, 2018). "Homeobox C8 (HOXC8) is a transcription factor preferentially overexpressed in a large percentage of non-small cell lung carcinoma (NSCLC)." (PMID 40701951, 2025).
cervical carcinoma (7 papers, 2014 to 2024). A carcinoma arising from either the exocervical squamous epithelium or the endocervical glandular epithelium. "Homeobox C8 (HOXC8) was a transcription factor that had been reported, and high expression of HOXC8 was associated with poor prognosis of cervical cancer." (PMID 35664768, 2022). "HOXC8/NAT10/FOXP1 promotes progression of cervical cancer and formation of suppressive immune microenvironment by regulating glucose metabolism." (PMID 39640362, 2024). "HOXC8 correlates negatively with tumour growth among pancreatic ductal adenocarcinomas, while showing increased expression in cervical cancers." (PMID 28402266, 2017). "For instance, high expression levels of HOXC8 and HOXC6 by immunohistochemistry were associated with poorer prognosis in a cohort of patients with esophageal squamous cell carcinoma, and increased gene expression was associated with worse outcome in cervical carcinoma." (PMID 32366326, 2020). "Studies in cervical cancer suggest it has a role in regulating cell proliferation and that it targets p27, FOXO1 and the (PI3K) AKT pathway, and HOXC8, a cell remodeling protein." (PMID 26544609, 2015).
ovarian carcinoma (6 papers, 2010 to 2023). A malignant neoplasm originating from the surface ovarian epithelium. "Inhibition of circNRIP1 reduced the paclitaxel resistance via targeting the miR-211-5p and HOXC8 (homeobox C8) in ovarian cancer." (PMID 38152652, 2023). "HOXC8 has been reported to be dysregulated in various types of cancer, including breast, cervical, prostate, and ovarian cancer, and acts as a transcription factor to regulate the transcription of many genes." (PMID 36650426, 2023). "Downregulation of circNRIP I suppresses the paclitaxel resistance of ovarian cancer via regulating the miR-2 I I-5p/HOXC8 axis." (PMID 35311096, 2022). "Previous findings demonstrated that HOXC8 depletion by small interfering RNA suppresses epithelial ovarian cancer proliferation and migration, and induces apoptosis by increasing ZAC1 expression." (PMID 32922885, 2018). "However, in various tumors, including ovarian cancer, hepatocellular carcinoma, and breast cancer, HOXC8 induces cell proliferation, migration and invasion, and is inversely correlated with overall survival (OS) through different mechanisms." (PMID 32922885, 2018).
glioma (5 papers, 2018 to 2025). A benign or malignant brain and spinal cord tumor that arises from glial cells (astrocytes, oligodendrocytes, ependymal cells). "This novel feedback loop between FMR1, circCHAF1A, miR-211-5p, and HOXC8 in glioblastoma stem-like cells can promote glioma proliferation and tumorigenesis." (PMID 40271197, 2025). "The present findings suggested that HOXC8 should be considered a novel biomarker and target for glioma treatment." (PMID 32922885, 2018). "The level of HOXC8 mRNA expression was negatively related with OS in all grade gliomas and grade IV gliomas (p < 0.05)." (PMID 32922885, 2018). "In this study, we demonstrated that si-HOXC8 blunted glioma cell proliferation, migration and invasion by reversing EMT." (PMID 32922885, 2018). "In U251 and LN229 glioma cells treated with small interfering RNA for HOXC8 (si-HOXC8) for gene knockdown, significantly lower cell capacity of growth, migration and invasion was observed." (PMID 32922885, 2018). "Small interfering RNA (si-HOXC8) was used to downregulate the mRNA and protein expression levels of HOXC8 to assess glioma cell proliferation, migration and invasion." (PMID 32922885, 2018). "The prognostic value of HOXC8 in glioma was further validated by qPCR and immunohistochemical data." (PMID 36650426, 2023). "In conclusion, we hypothesized that HOXC8 could serve as a novel biomarker for predicting glioma OS." (PMID 32922885, 2018). "Interestingly, the six glioma cell lines showed higher HOXC8 expression levels compared with HA cells (human astrocytes)." (PMID 32922885, 2018). "In gliomas, the mechanism by which HOXC8 affected EMT is unclear." (PMID 32922885, 2018). "In agreement, HOXC8 knockdown inhibited glioma cell proliferation." (PMID 32922885, 2018). "To assess whether the migration and invasion capacity of glioma cells could be inhibited by si-HOXC8, we performed migration and Matrigel invasion assays using LN229 and U251 cells." (PMID 32922885, 2018). "HOXC8 knockdown could inhibit glioma cell proliferation, migration and invasion." (PMID 32922885, 2018). "Although HOXC8 is important in tumorigenesis, its mechanism in glioma remains unclear." (PMID 32922885, 2018). "HOXC8 may play an important role in glioma proliferation, migration and invasion." (PMID 32922885, 2018). "Based on the Chinese Glioma Genome Atlas (CGGA) set, HOXC8 expression is negatively correlated with overall survival (OS)." (PMID 32922885, 2018). "Then, the results from multivariate Cox regression analysis including HOXC8 expression, age at diagnosis, IDH1 status, gliomas grade and TCGA subtype showed that HOXC8 was an independent prognostic factor for glioma patients (p < 0.0001, HR = 1.247)." (PMID 32922885, 2018). "Therefore, HOXC8 could provide novel insights for glioma treatment." (PMID 32922885, 2018). "Crystal violet staining showed markedly less migration and invasion glioma cells after HOXC8 silencing compared with negative-control values (p < 0.01)." (PMID 32922885, 2018). "The RBP FMRP can also bind to circular RNA CHAF1A (circCHAF1A) and promote its expression by maintaining its stability, while homeobox C8 (HOXC8) also transcribes FMRP expression to form a feedback loop, which may be involved in the malignant transformation of glioma." (PMID 40271197, 2025).
hepatocellular carcinoma (5 papers, 2018 to 2022). A malignant tumor that arises from hepatocytes. "In patients with hepatocellular carcinoma, HOXC8 expression is related to poor survival and recurrence." (PMID 33557848, 2021). "HOXC8, overexpressed in hepatocellular carcinoma (HCC) compared with adjacent non-tumor tissues, is associated with poor prognosis." (PMID 32922885, 2018).
pancreatic cancer (5 papers, 2011 to 2020). "Consistent with this, HOXC8 has been implicated in different cancer types, including prostate, cervical, breast, oesophageal, and pancreatic cancer." (PMID 28202042, 2017). "The expression of HOXC8 in 14 of 15 human pancreatic cancer cell lines was inversely related to their ability to grow in the liver of nude rats." (PMID 21712827, 2011). "Also, HOXC8 expression has been shown to be inversely correlated with metastasis in pancreatic cancer." (PMID 32366326, 2020). "Finally, the relationship of HOXC8 to OPN- or ON-expression levels was to be determined in pancreatic cancer cell lines and related to their growth in vivo." (PMID 21712827, 2011). "With regard to OPN, there was a significantly inverse relation between the mRNA-expression levels of Hoxc8 and OPN in 12 of 14 human pancreatic cancer cell lines investigated." (PMID 21712827, 2011). "Colony formation was used for studying the effect of HOXC8 down-regulation on the ability of Suit2-007, Panc-1 and MIA PaCa-2 pancreatic cancer cells to form clusters of >30 cells." (PMID 21712827, 2011). "The levels of Hoxc8 mRNA were high in DANG, Panc-1 and Suit2-007 pancreatic cancer cells, relatively high to moderate in A8 18–4, MIA PaCa-2, Capan 1, Patu 390, as well as SU 8686 cells, and low to very low in CFPAC, Aspc-1, Panc-89, Colo-357, ASML, S2013 and BxPc-3 cells." (PMID 21712827, 2011).
breast tumor (4 papers, 2014 to 2018). "The analysis of publically available human breast tumor microarray gene expression database demonstrates a strong positive linear association between HOXC8 and CDH11 expression (ρ = 0.801, p < 0.001)." (PMID 24810778, 2014). "Analysis of breast tumor sample microarray database reveals that the expression HOXC8 and CDH11 are in a strong positive linear association." (PMID 24810778, 2014). "miRNA-196 family was also reported as potent metastasis suppressors and revealed that the ratio of miR-196 family to HOXC8 mRNA is an indicator of the metastatic capability of breast tumors." (PMID 30326837, 2018). "Strong correlation between HOXC8 and CDH11 expression in clinical breast tumor specimens is also in agreement that HOXC8 is a CDH11 transcription factor." (PMID 24810778, 2014). "Moreover, the findings that both high HOXC8 and CDH11 expression correlate with poor recurrence-free survival of breast cancer patients further support the notion that the HOXC8-CDH11 functional axis plays a critical role in breast tumor progression and metastasis." (PMID 24810778, 2014).
gastric cancer (3 papers, 2020 to 2023). A primary or metastatic malignant neoplasm involving the stomach. "The high HOXC8/high SPP1 group was associated with shorter overall survival than the low HOXC8/low SPP1 group was among gastric cancer patients." (PMID 37670969, 2023). "To determine the effects of HOXC8 on gastric cancer cell proliferation and migration, we performed the loss-of-function assay." (PMID 35111675, 2021). "The high HOXC8/high OPN expression group was associated with shorter overall survival compared to that of the low HOXC8/high OPN expression group among gastric cancer patients." (PMID 37670969, 2023). "Next, we evaluated the effect of HOXC8 on cell viability and colony formation in gastric cancer cells." (PMID 37670969, 2023). "We found that HOXC8 was amplified in gastric cancer tissues, and mRNA expression levels were significantly associated with tumor status (P=0.044) and poor overall survival (P<0.01)." (PMID 37670969, 2023). "We found that HOXC8 expression correlates with poor overall survival in gastric cancer patients, indicating that HOXC8 is an independent prognostic factor." (PMID 37670969, 2023). "A high level of HOXC8 expression correlated with the overall survival rate in patients with gastric cancer." (PMID 37670969, 2023). "The EdU incorporation assay was used to determine gastric cancer cell proliferation, and HOXC8 knockdown reduced the number of EdU-positive BGC-823 and AGS cells when compared to the control groups." (PMID 35111675, 2021). "Knockdown of HOXC8 and overexpression of miR-4256 both significantly repressed the gastric cancer cell proliferation and migration, and miR-4256 repressed the expression of HOXC8 via targeting its 3’ untranslated region in gastric cancer cells." (PMID 35111675, 2021). "The functional studies showed that knockdown of HOXC8 suppressed gastric cancer cell proliferation, viability and migration." (PMID 35111675, 2021). "Among these hub genes, we performed the in vitro functional studies of HOXC8 in gastric cancer cells." (PMID 35111675, 2021). "The mRNA expression of HOXC8 was up-regulated in the gastric cancer cells when compared to GES-1 cells." (PMID 35111675, 2021). "Among these hub genes, we performed the in vitro functional studies of HOXC8 in the gastric cancer cells." (PMID 35111675, 2021). "Collectively, our results indicated that miR-4256 acts as a tumor suppressor in gastric cancer cells by repressing HOXC8." (PMID 35111675, 2021). "Therefore, we evaluated the effect of HOXC8 on proliferation and colony formation in gastric cancer cells." (PMID 37670969, 2023). "HOXC8 knockdown significantly reduced the viability of gastric cancer cell lines." (PMID 37670969, 2023). "In conclusion, HOXC8 may be an independent prognostic factor and serve as a useful predictive biomarker for gastric cancer." (PMID 37670969, 2023). "First, we examined the expression levels of HOXC8 in gastric cancer cell lines." (PMID 37670969, 2023). "In our study, the highest expression of HOXC8 was observed in gastric cancer tissues." (PMID 37670969, 2023). "Additional functional assays indicated that a novel miR-4256/HOXC8 signaling axis may involve the progression of gastric cancer." (PMID 35111675, 2021). "Among the hub genes, we further examined the in vitro functions of HOXC8 in the gastric cancer cells and found that HOXC8 was up-regulated in the gastric cancer cells, suggesting that HOXC8 may act as an oncogene in gastric cancer." (PMID 35111675, 2021). "Collectively, our results revealed that complex interaction networks of differentially expressed genes in gastric cancer, and further functional studies indicated that miR-4256/HOXC8 may be an important axis in regulating gastric cancer progression." (PMID 35111675, 2021). "Consistently, our results showed that miR-4256 could negatively regulate the expression of HOXC8 in gastric cancer cells, and suppressed the proliferation and migration of gastric cancer cells." (PMID 35111675, 2021).